PARP1 (poly(ADP-ribose) polymerase 1)
Diseases named in the same sentence as PARP1 in open-access papers (continued):
Sharing a sentence is not in itself a finding about the gene and the disease.
breast cancer (continued). "Similar to the breast cancer cells, the colorectal cancer cells showed inhibition of PARP1 function and accumulation of DNA damage." (PMID 39456564, 2024). "The complex heterogeneity of breast cancer emphasizes the importance of assessing PARP1 expression in vivo to optimize the personalized and effective use of PARP1 inhibitors in therapy." (PMID 39768978, 2024). "UTP6 was enriched in the process of snoRNA binding, while snoRNA activated PARP-1 ADPRylates DDX21 in BRCA1/2-wild-type breast cancer cells to promote enhanced ribosome biogenesis and cell proliferation." (PMID 39095659, 2024). "The results showed that JAK2, HPGDS, AR and PARP1 had good potential for targeted treatment of breast cancer." (PMID 38872110, 2024). "A second olaparib-based PROTAC, LB23, also induced PARP1 degradation in addition to cell-cycle arrest in the G2/M phase in breast cancer cells." (PMID 38791105, 2024). "It has been demonstrated that Ibrutinib induces breast cancer cell death through apoptosis (caspase-dependent), culminating in the modulation of caspase 3, caspase 8, and PARP1." (PMID 38790974, 2024). "Collectively, our systematic efforts to design lead-like moleculeshave the potential to open doors for the exploration of dual PARP1-BRD4inhibitors as a promising avenue for breast cancer treatment." (PMID 39292752, 2024). "It has shown potential as a PET-based biomarker for imaging PARP-1 expression in breast cancer and ovarian cancer." (PMID 38338854, 2024). "The DNA repair gene PARP1 and NF-κB signalling pathway affect the metastasis of breast cancer by influencing the drug resistance of cancer cells." (PMID 38388665, 2024). "Calycosin (100 μM) regulates the expression of ERβ, IGF‐1R, PI3K/Akt, and PARP‐1, inducing apoptosis and control of cell proliferation in multiple breast cancer cells." (PMID 38230908, 2024). "Cox regression analysis showed that high expression levels of PARP1 and TNF-α were a risk factor for distant metastasis after breast cancer surgery (RRPARP1 = 4.092, 95% CI 2.475–6.766, P < 0.001; RRTNF-α = 1.825, 95% CI 1.189–2.799, P = 0.006)." (PMID 38388665, 2024). "Early work established that PARPi resistance can develop in a subset of breast cancer patients by reversion mutations in the BRCA1/2 genes that restore HR function and thereby abrogate cellular dependence on PARP1/2." (PMID 38956205, 2024). "Based on TCGA and GEO datasets analysis, we found that PARP1 was significantly upregulated in breast cancer." (PMID 36941223, 2023). "Meanwhile, the PARP1 inhibitor Olaparib enhances clock gene expression, thus, reducing breast carcinogenesis, indicating that PARP1 inhibitors have potential antitumor effects in high‐PRMT6 expression breast cancer." (PMID 36941223, 2023). "In contrast, p-YB-1 and PARP1 increased consistently when breast cancer cell lines were treated with abemaciclib." (PMID 38037159, 2023). "For example, our previous IP studies had identified the early DNA damage sensor PARP1 as an interaction partner of HMGA2 in human breast cancer cells." (PMID 36835656, 2023). "PARP1 and p-YB-1 protein levels in breast cancer cells and tissues were quantified using Western blot (WB) analysis, immunohistochemical staining (IHC) and immunofluorescence (IF) assays." (PMID 38037159, 2023). "Research has shown that the application of PARP-1 inhibitor AG14361 on breast cancer cell lines, which constitutively express NF-kB, successfully suppressed the expression of a luciferase reporter gene activated by ionizing radiation." (PMID 37351512, 2023). "On the contrary, there are studies in pancreatic and breast cancer that differ in how PARP-1 affects survival, suggesting that high PARP-1 expression is associated with better survival." (PMID 36902215, 2023). "The idea of co-targeting ERα and PARP1 is supported by reports that showed that a combination of tamoxifen and talazoparib sensitized breast cancer cells to tamoxifen through the reduction of ERα poly-ADP-ribosylation." (PMID 36869202, 2023).
breast cancer (continued). "Here, we demonstrate, for the first time, that SOC therapies used in ER+ breast cancer induce DNA damage, and toxic PARP1 trapping upon generation of a functional BRCAness phenotype through loss of key DNA repair proteins, including BRCA1, BRCA2 and RAD51." (PMID 37914699, 2023). "A previous report also investigated the response to MK-1775 and talazoparib, a highly potent orally active PARP-1/2 inhibitor used to treat breast cancer." (PMID 37370065, 2023). "The co‐staining results indicated that PRMT6 and PARP1 abundances were elevated in breast cancer samples and were positively correlated with histological grades." (PMID 36941223, 2023). "BRCA-associated breast cancers have demonstrated a dependence on alternate DNA repair processes through base excision repair, which requires poly (ADP-ribose) polymerase 1 (PARP-1)." (PMID 37958970, 2023). "Both MRE11 and NBS1 depletion increases sensitivity to PARP-1 inhibitor KU 58948 in breast cancer cell lines." (PMID 37509263, 2023). "The published datasets were analyzed to better understand the association between PRMT6, PARP1, DDB1, and PER3 in breast cancer." (PMID 36941223, 2023). "Compounds acting as CDK-1 and/or PARP-1 inhibitors can induct cell death in breast cancer with a selective synthetic lethality mechanism." (PMID 37762072, 2023). "The data from multiple immunofluorescence (MIF) assays indicated that p-YB-1 and PARP1 were coexpressed and colocalized in four representative breast cancer patients." (PMID 38037159, 2023). "Yoon, J. H. reported that autophagy through DNA repair regulated by AMPK activation of PARP‐1 contributed to the sustained survival of breast cancer cells." (PMID 36919822, 2023). "Meanwhile, PER3 protein abundance was decreased, and was inversely correlated with the abundance of PRMT6 and PARP1, in breast cancer samples." (PMID 36941223, 2023). "The expression of p-YB-1/PARP1 and the abemaciclib IC50 were positively correlated in seven breast cancer cell lines based on the quantitative analysis results of the protein level of p-YB-1/PARP1 and IC50 detection." (PMID 38037159, 2023). "Here, we show, for the first time, that SOC therapies used in ER+ breast cancer (here: tamoxifen, fulvestrant and palbociclib) induce DNA damage along with inhibition of homologous recombination (HR) and toxic PARP1 trapping." (PMID 37914699, 2023). "The 30 breast cancer cell lines were divided into two groups based on the level of PARP1 mRNA, and those with a high level of PARP1 demonstrated a tendency to have a higher palbociclib IC50." (PMID 38037159, 2023). "To investigate the regulation of PRMT6 and PARP1 in breast cancer tissues, we assessed their protein levels in breast carcinoma samples of different histological grades, as well as in normal mammary tissues via IHC staining assays." (PMID 36941223, 2023). "A mixed treatment by means of CDK-1 and PARP-1 inhibitors resulted in radical breast cancer cell growth reduction." (PMID 37762072, 2023). "Targeted DDR therapy has emerged as a potential therapeutic approach for breast cancer, with PARP-1 inhibitors serving as an approved example." (PMID 37448962, 2023). "Lestaurtinib, a tyrosine kinase inhibitor, enhanced the in-vitro drug effects of the PARP1 inhibitor AG14361 in breast cancer treatment, partly by suppressing NF-κB signaling." (PMID 37508580, 2023). "PRMT6 and PARP1 expression were elevated in breast cancer samples and were positively correlated with histological grade." (PMID 36941223, 2023). "The inhibition of CXCR4 reduced growth, migration, and invasion in mouse models carrying breast cancer, and the anti-tumor effect of PARP1 inhibitors was also enhanced when CXCR4 was inhibited." (PMID 37550554, 2023). "Bromelain also has radiosensitizing effects and can significantly reduce tumor volume and PARP-1, Ki-67, and NF-κB levels while significantly increasing ROS content and lipid peroxidation in breast carcinoma cells." (PMID 37262048, 2023).
breast cancer (continued). "The synthesis, characterization, and efficacy of new thiouracil amides were therefore investigated herein and found a lead compound 5e that inhibits both PARP1 catalytic activity and breast cancer cell viability." (PMID 35566199, 2022). "Previous studies have reported that PARP1 inhibitor Olaparib inhibits many tumor cell growth, like pancreatic cancer 31, prostate cancer 32 and breast cancer." (PMID 35517402, 2022). "Inhibition of PARP-1 in cancer has led to the marketing of four PARP-1 inhibitors for breast cancer and ovarian cancer, namely, Olaparib, Rucaparib, Niraparib, and Talazoparib." (PMID 35158955, 2022). "Olaparib is an example of PARP1 inhibitor that has been shown to provide a significant benefit over standard chemotherapy for metastatic, germline BRCA mutated HER2-negative breast cancers." (PMID 35768871, 2022). "Although olaparib, a new PARP1 inhibitor developed by AstraZeneca, was approved by the FDA in 2018 for the treatment of breast cancer patients with hereditary BRCA gene mutations, the toxicity and treatment resistance of olaparib still exist." (PMID 35463096, 2022). "Protein expression of PARP1, X-ray cross complementing protein 4/1 (XRCC4, XRCC1), and ERCC1 were risk factors for postoperative metastasis of breast cancer." (PMID 36612206, 2022). "Inhibition of PARP1 expression and activity has been shown to reverse the resistance to chemotherapy and radiotherapy in multiple tumors, such as breast cancer and pancreatic cancer." (PMID 35875162, 2022). "Increased nuclear PARP1 protein has been correlated with decreased relapse-free and overall survival in breast cancer and AML80,81." (PMID 36344544, 2022). "Very recently, germline mutational status of the DNA-repair genes breast cancer 1 and 2 (gBRCA1/2) has been shown to be predictive of response to the poly(ADP-ribose)-polymerase 1 (PARP1)-inhibitor olaparib in early-stage HER2-negative breast cancer patients." (PMID 35837334, 2022). "In breast cancer cells, PARP1 competes with histone H1 to maintain transcription of the oncogene CCND1 (encoding cyclin D1), and also acts as a transcriptional coactivator of GATA binding protein 3 (GATA3), thus promoting the transcription of CCND1." (PMID 36566215, 2022). "We then examined clinical patient samples from our institution (Indiana University Melvin and Bren Simon Comprehensive Cancer Center Tissue Bank) and also demonstrated high PARP1 expression in breast cancer and low PARP1 expression in lung cancer." (PMID 36203459, 2022). "CYD-4-61 was also reported to activate Bax protein, promote the release of Cyt-C and boost the cleavage of PARP-1 and caspase-3, thus inducing breast cancer cells apoptosis." (PMID 35414025, 2022). "At the time of going to press, PARP-1 inhibitors are a targeted therapy for the treatment of breast cancer gene (BRCA)-mutated ovarian and breast cancers." (PMID 35158955, 2022). "It has been reported that DNMT1 interacts with PARP1 to regulate the sensitivity of breast cancer and acute myeloid leukemia cells to PARP inhibitors." (PMID 34854226, 2022). "In this regard, encouraging results derive from a PET imaging study aimed at quantifying PARP-1 expression in 13 breast cancer patients using a radiolabeled tracer with a chemical structure similar to PARPi." (PMID 36428727, 2022). "As PARP1 is associated with single-strand break repair, base-excision repair, and NHEJ, other than HR in DDR, PARP1 inhibition in HR-deficient cells, such as breast cancer gene 1/2 mutants, is effective in treating cancers." (PMID 35741087, 2022). "In the mutation driver module for breast cancer, both BRCA1 and BRCA2 are exactly connected to PARP1." (PMID 36266635, 2022). "Olaparib, the first PARPi approved by FDA that targets PARP1/2, is effective against advanced ovarian cancer and breast cancer." (PMID 35726713, 2022). "PARP1 inhibition was found to radiosensitize breast cancer models to ionizing radiotherapy preclinically." (PMID 36387071, 2022).
breast cancer (continued). "Over the past decade, Poly (ADP-ribose) polymerase-1 (PARP-1) inhibitors have arisen as a novel and promising targeted therapy for breast cancer gene (BRCA)-mutated ovarian and breast cancer patients." (PMID 35158955, 2022). "The ELISA assay showed that YHP-836 dose-dependently reduced intracellular PAR levels in MX-1 breast cancer cells, which reflected the catalytic activity of PARP1 and PARP2." (PMID 35910366, 2022). "In breast cancer, high ALDH activity is associated with overexpression of poly (ADP-ribose) polymerase 1 (PARP1) and Olaparib resistance." (PMID 35299840, 2022). "NUDT5 generates ATP in the nucleus of breast cancer cells in response to progesterone, dependent on degradation of PARP1 synthesize PAR to ADPR by PARG." (PMID 33668737, 2021). "In preclinical experiments on breast cancer cell lines, small-molecule PARP1/PD-L1 inhibitor conjugates demonstrated more significant apoptosis and cytotoxic efficacy compared to their separate agents." (PMID 34531868, 2021). "For example, on the top screen of PICKLES, check “Breast cancer” in the “Cancer type” field, enter “PARP1” in the “Primary gene” field, and “BRCA1” in the “Secondary gene” field (the results of mutation and copy number are reflected in the Secondary gene)." (PMID 34830205, 2021). "In melanoma, breast cancer, lung cancer, and other neoplastic diseases, the expression of PARP1 is often increased." (PMID 33747905, 2021). "We chose to test niraparib, an FDA-approved PARP1/2 inhibitor that is currently under evaluation in breast cancer clinical trials." (PMID 33470989, 2021). "In recent years, the role of NUDT5 in the biology of breast cancer cells has attracted our attention in the context of our studies on the function of the poly-ADP-Ribose (PAR) synthesis by PARP1 for the hormonal gene regulation." (PMID 33668737, 2021). "Patients with breast cancer had the highest frequency of PARP1 alterations (12.35%), and most of the alterations were amplification (11.82%, 545/4609)." (PMID 34531868, 2021). "Elevated PARP-1 expressions have been reported in a wide range of human cancers including breast cancer, and an especially high PARP-1 expression has been found found in TNBC which can explain our results." (PMID 33669671, 2021). "Patient-derived xenograft (PDX) models were used to assess the sensitivity of breast cancers with active MEIOB to PARP1 inhibitors." (PMID 33628586, 2021). "Tumor cells that are defective in either of the breast cancer susceptibility genes (i.e., BRCA1 or BRCA2) are sensitive to the inhibition of PARP1." (PMID 34359565, 2021). "We assessed E-cadherin, N-cadherin, and PARP-1 protein expression in mammary tumor cell lines MDA-MB-468 and CF41 by immunofluorescence." (PMID 34947958, 2021). "Bleomycin hydrolase and poly(ADP-ribose) polymerase-1 are reported to participate in the Ubc9-mediated resistance against chemotherapy agents in human breast carcinoma MCF-7 cells." (PMID 33499132, 2021). "In recent years, the successful development of PARP1/2 inhibitors has provided effective treatment options for ovarian cancer (OC) and breast cancer (BC)." (PMID 34976832, 2021). "In summary, PARP-1 is a key regulator of the aromatase promoter I.3/II activity, which can be activated in BAFs by metabolic coupling to breast cancer cells." (PMID 32059481, 2020). "Results from Egyptian researchers also demonstrated that PARP1 immunohistochemical expression is predictive of response to anthracycline/taxane based neoadjuvant chemotherapy in locally advanced breast cancer patients." (PMID 32355298, 2020).
breast cancer (continued). "In the TCGA breast cancer data, (U.C. Santa Cruz, xenabrowser.net, Nature 2012), two of the factors in this study (PARP1 and CCL2) showed significant overexpression in the Basal type of tumors concerning the Luminal-A or B subtype." (PMID 32455851, 2020). "According to the network results and consulting numerous references, c-Met and PARP-1 were manually selected as the key targets in breast cancer." (PMID 32201536, 2020). "Since CCL2 mediated cell signaling pathway activation and PARP1 inhibition are negatively correlated in breast cancer cells, we compared whole transcriptome profiles of MB-231 with rhCCL2 or PJ34 treatment." (PMID 32455851, 2020). "We examined the total levels of PAR and PARP1 in cell lysates from different subtypes of breast cancer cells." (PMID 32455851, 2020). "It was also successfully validated in vitro and in vivo breast cancer models to image PARP1 expression levels and has progressed to clinical trials." (PMID 32640708, 2020). "In the current study, based on systems biology approaches and numerous literature researches, we manually selected c-Met and PARP-1 as the key targets in breast cancer." (PMID 32201536, 2020). "In this study, multiple approaches including microarray analysis, biological characteristics were utilized to screen the hub proteins, and c-Met/PARP-1 were considered as the most effective drug targets in the context of breast cancer." (PMID 32201536, 2020). "It has been reported that PARP1 expression was correlated to clinicopathological variables and outcome of breast cancer patients." (PMID 32355298, 2020). "PARP1 and PARP2 play critical roles in regulating DNA repair and PARP inhibitors have been approved for the treatment of BRCA1/2-mutated ovarian and breast cancers." (PMID 32029902, 2020). "The expression of KLF4 and PARP1 is also significantly correlated with each other in these 117 cases of breast cancer tissues." (PMID 33231937, 2020). "In the case of breast cancer, several clinical studies combining chemotherapy or radiation therapy with PARP-1 inhibitors are ongoing but limiting adverse events have been reported in several instances." (PMID 33158305, 2020). "NAM-induced SIRT1 or PARP1 suppression also enhances sensitivity to chemotherapy in breast cancer cell lines." (PMID 32245130, 2020). "Along with that, post-transcriptional cytokine mRNA stabilization by PARP1 can be another level of control in the context of breast cancer." (PMID 32455851, 2020). "We identified the function and target of H19 in regulating chemotherapy response both in cell lines and in clinical samples, providing evidence that H19 targets PARP-1 to mediate the chemotherapeutic resistance of breast cancer cells." (PMID 32345117, 2020). "In this study, a series of bioinformatics approaches were performed to identify the hub proteins, and then c-Met and PARP-1 were identified as the vital targets in breast cancer." (PMID 32201536, 2020). "It is worth noting that PARP1 inhibitors have been approved by the Food and Drug Administration to treat several type of cancer, such as breast cancer." (PMID 32475059, 2020). "After consulting numbers of references, c-Met and PARP-1 were considered as the key targets in breast cancer." (PMID 32201536, 2020). "While breast cancer tumors with BRCA mutations are more susceptible to treatment with PARP1 inhibitors, there is still a great clinical need for novel drugs that can be used to treat advanced BRCA-mutated breast cancer." (PMID 32620799, 2020). "All these findings led to extensive investigations to evaluate the potential of DDR-targeting drugs for prostate and breast tumors which culminated in the approval of PARP-1 inhibitors for breast cancer and, very recently, also for prostate cancer." (PMID 33158305, 2020).